WDR75 (WD repeat domain 75)
Description:
Ribosome biogenesis factor. Part of the small subunit (SSU) processome, first precursor of the small eukaryotic ribosomal subunit. During the assembly of the SSU processome in the nucleolus, many ribosome biogenesis factors, an RNA chaperone and ribosomal proteins associate with the nascent pre-rRNA and work in concert to generate RNA folding, modifications, rearrangements and cleavage as well as targeted degradation of pre-ribosomal RNA by the RNA exosome. Involved in nucleolar processing of pre-18S ribosomal RNA. Required for optimal pre-ribosomal RNA transcription by RNA polymerase I.
Synonyms: UTP17; FLJ12519; NET16
Tractability: Small molecule: a structure with a bound ligand is known. PROTAC: UniProt records ubiquitination sites on it; ubiquitination databases record sites on it; its protein half-life has been measured.
Gene: Protein-coding gene on chromosome 2 (189,441,429 to 189,479,063, forward strand). Ensembl gene ENSG00000115368.
Subcellular location: Nucleus, nucleolus
Pathways (Reactome):
Metabolism of RNA: Major pathway of rRNA processing in the nucleolus and cytosol; rRNA modification in the nucleus and cytosol
Gene Ontology:
Molecular function: protein binding; RNA binding
Biological process: positive regulation of rRNA processing; positive regulation of transcription by RNA polymerase I; ribosomal small subunit biogenesis; maturation of SSU-rRNA; ribosome biogenesis
Cellular component: nucleolus; small-subunit processome; nucleoplasm; t-UTP complex
Genetic constraint (gnomAD): Loss-of-function variants: 41 observed, 95.65 expected, observed/expected ratio (o/e) 0.43, 90% interval 0.33 to 0.56. The upper end of that interval is the gene's LOEUF score, 0.56, which puts it in group 2 of 6, group 1 being the genes least tolerant of losing a copy. Missense variants: 821 observed, 918.8 expected, observed/expected ratio (o/e) 0.89, 90% interval 0.84 to 0.95. Synonymous variants: 306 observed, 321.4 expected, observed/expected ratio (o/e) 0.95, 90% interval 0.87 to 1.05.
Homologues: Orthologues: chimpanzee WDR75 (99% identical), macaque WDR75 (99% identical), pig WDR75 (91% identical), rabbit WDR75 (91% identical), dog WDR75 (91% identical), guinea pig WDR75 (89% identical), mouse Wdr75 (85% identical), rat Wdr75 (84% identical), tropical clawed frog wdr75 (59% identical), zebrafish wdr75 (54% identical). Paralogues in human: WDR62 (14% identical), MAPKBP1 (14% identical), WDR7 (12% identical), TEP1 (12% identical), AHI1 (10% identical), POC1B (9% identical), WDR81 (9% identical), WDR27 (9% identical), NWD1 (9% identical), WDR17 (9% identical), SNRNP40 (8% identical), DCAF4 (8% identical), and 14 more.
Diseases named in the same sentence as WDR75 in open-access papers:
WDR75 is named in the same sentence as 8 diseases in open-access papers, as found by Europe PMC text mining. Sharing a sentence is not in itself a finding about the gene and the disease. The quoted sentences say what the papers report.
Sepsis (2 papers, 2023 to 2024). Sepsis is defined as life-threatening organ dysfunction caused by a dysregulated host response to infection. "The current mechanism of action of WDR75 and TBL3 in patients with sepsis is unclear, and further studies are needed." (PMID 39438952, 2024). "Microarray analysis has indicated abnormalities in the expression of immune-related genes in children with sepsis, including FYN, FBL, ATM, WDR75, FOXO1, and ITK." (PMID 36855207, 2023).
cardiac hypertrophy (1 paper, 2012). "Up-regulated genes bound by TWIST1 included the two pore channel Tpcn1; the Rho activating protein, Abra, which has been implicated in cardiac hypertrophy; the kinase Sik1; and the uncharacterized genes Gatsl2 and Wdr75." (PMID 22815831, 2012).
fibrosarcoma (1 paper, 2025). A malignant mesenchymal fibroblastic neoplasm affecting the soft tissue and bone. "Notably, WDR75 showed the strongest association with rapidly accelerated fibrosarcoma (RAF), while DNTTIP2 and BRIX1 were most closely related to CTLA4." (PMID 40577282, 2025).
cancer (3 papers, 2022 to 2025). A tumor composed of atypical neoplastic, often pleomorphic cells that invade other tissues. "Current knowledge of WDR75 is still very limited, and studies on its association with disease are limited to a few cancers." (PMID 39438952, 2024).
tumor (2 papers, 2017 to 2025). "Among these 13, TASOR2 pS1025 and WDR75 pS782 also exhibited significant differences between tumor stages (stage 1 versus others)." (PMID 39793886, 2025).
WDR75 also shares sentences with these, for which no sentence is quoted: hepatocellular carcinoma (1 paper); infection (1); prostate carcinoma (1).